CXCR2 (C-X-C motif chemokine receptor 2)
Diseases named in the same sentence as CXCR2 in open-access papers (continued):
Sharing a sentence is not in itself a finding about the gene and the disease.
melanoma (continued). "Here, we have also demonstrated that overexpression of CXCR1 or CXCR2 in CXCL-8-expressing melanoma cells potentiates ERK1/2 MAP kinase signalling." (PMID 19401689, 2009). "Interestingly, the inhibition of CXCR2 in a melanoma mouse study resulted in a reduction in NK cell tumor infiltration and an enhancement of the survival rate of melanoma-bearing mice." (PMID 39339180, 2024). "We next utilized the RNAseq data from Braf/Pten mice with or without loss of CXCR2 to identify the most differentially expressed genes that are associated with favorable or unfavorable outcome in melanoma patients." (PMID 37270599, 2023). "To define the relationship between CXCR2 expression and the clinical prognosis of melanoma patients, we examined clinical data from the Cancer Genome Atlas (TCGA), and the skin cutaneous melanoma (SKCM) dataset using Gene Expression Profiling Interactive Analysis (GEPIA)." (PMID 37270599, 2023). "In addition, the effects of a CXCR1/CXCR2 antagonist, SX-682, on melanoma tumorigenesis were evaluated in BrafV600E/Pten−/− and NRasQ61R/INK4a−/− mice and in melanoma cell lines." (PMID 37270599, 2023). "When Cxcr1/Cxcr2 were antagonized in Braf/Pten mice and tumorigenic melanoma cell lines via treatment with SX-682, similar alterations in tumor growth and the gene expression profiles were achieved, and this was accompanied by development of anti-tumor immune microenvironment." (PMID 37270599, 2023). "Moreover, CXCR1/CXCR2 antagonists combined with anti-PD-1 are currently in clinical trials for the treatment of melanoma (NCT03161431)." (PMID 37270599, 2023). "Our data support combining CXCR1/CXCR2 antagonists with immunotherapy for melanoma patients." (PMID 37270599, 2023). "In addition, it has previously been reported that this axis promotes chemotherapy resistance in melanoma, as dacarbazine chemotherapy‐induced upregulation of CXCR2 by a nuclear factor kappa B (NF‐κB)‐dependent mechanism." (PMID 37170733, 2023). "More significant therapeutic effects were observed in B16 melanoma bearing mice treated with three-drug combination of hydroquinone (Hy), CXCR2 inhibitor (SB225002, CXCR2i) 49, 50, 52 and PD1 mAb, as manifested by the prolonged survival time and reduced tumor burden in the lung and brain." (PMID 35265199, 2022). "Several studies found that upregulation of CXCR1 or CXCR2 resulted in an increase of melanoma cell proliferation and invasion, while knockdown of CXCR1 and/or CXCR2 led to inhibition of melanoma cell growth, motility, and vascularization both in vitro and in vivo." (PMID 36612163, 2022). "The expression of CXCR2 in primary T cells enhanced migration toward both recombinant and melanoma-tumour-derived CXCL1 in vitro, and the surface expression of CXCR2 enhanced the accumulation of T cells in tumours in a mouse model of melanoma, improving tumour regression and survival." (PMID 35205725, 2022). "For example, CXCR2 is better expressed in melanoma than in neutrophils, which automatically increases IL-8 binding to tumor instead to immune cells with all the subsequent events which may arise from this." (PMID 35011682, 2021). "Comparing the expression of CXCR2 on other melanoma infiltrating immune cells, including CD8+ T cells, dendritic cells (DC), macrophages, NK cells, Treg, and M-MDSC, we found it almost ubiquitously present on PMN-MDSC but only to a very low extent on other cell populations." (PMID 33578808, 2021). "Importantly, the treatment with CXCR2 inhibitor significantly prolonged the survival of mice with resected primary melanomas." (PMID 33578808, 2021). "Furthermore, blocking of CXCR2 in vitro completely abolished the recruitment of PMN-MDSC by CXCL1-secreting Ret melanoma cells." (PMID 33578808, 2021). "The observed therapeutic effect in melanoma bearing mice was associated with the accumulation of NK cells while no involvement of effector T cells in response to anti-CXCR2 therapy was found." (PMID 33578808, 2021).
melanoma (continued). "Indeed, we further identified patients with anti-PD-1-resistant melanoma to exhibit elevated HSP70 plasma levels as well as an increase in the myeloid-associated genes, CD33, CD11B, CXCR2, S100A8, and S100A9, in tumor tissue specimens relative to responders." (PMID 34638239, 2021). "To investigate if melanoma cells are capable of recruiting PMN-MDSC via CXCR2 from the periphery, we cultured Ret melanoma cells in the bottom compartment of a transwell and determined the number of migrated PMN-MDSC towards Ret cells through SVEC4-10 lymphatic endothelial cells." (PMID 33578808, 2021). "Taken together, these data support a prominent role of CXCR2/CXCL1 axis in the recruitment of PMN-MDSC in melanoma, indicating this receptor as an ideal target for blocking migration of these cells without impairing the trafficking of tumor-reactive effector immune cells." (PMID 33578808, 2021). "Indeed, we observed that the application of the CXCR2 inhibitor in the adjuvant setting after resection of primary melanomas diminished the number of macroscopic metastatic nodules in lungs and liver and markedly prolonged mouse survival." (PMID 33578808, 2021). "The effect of CXCR2 on cell proliferation was shown in melanoma ovary and prostate cancers." (PMID 34038868, 2021). "Next, we tested the effect of CXCR2 inhibition on melanoma progression in vivo." (PMID 33578808, 2021). "This may be due to the lower frequency of CXCR2+ M-MDSC (30%) than that of CXCR2+ PMN-MDSC infiltrating melanoma." (PMID 33578808, 2021). "Using the RET transgenic mouse melanoma model, which resembles melanoma development in patients, we found a significant reduction of PMN-MDSC in the tumor microenvironment that was associated with a survival benefit upon the therapy with the CXCR2 inhibitor." (PMID 33578808, 2021). "In the context of rTCR-T cells, it was found that co-expression of CXCR2 with MAGE-A3 specific TCRs could significantly enhance migration to the tumor site in a mice model of melanoma, resulting in reduced tumor growth." (PMID 33287413, 2020). "Although CXCR2 participates in melanoma metastasis, only a few studies for CXCR2P are available." (PMID 33336008, 2020). "Similarly, expression of CXCR2 in transgenic pmel-1 or MAGE-A3 T-cell receptor-engineered T-cells enhanced their ability to migrate to subcutaneous xenografts of melanoma and colonic origin." (PMID 31091832, 2019). "When high levels of the IL-8 receptor CXCR2 are present in melanomas, an enhanced metastatic potential could be determined." (PMID 31565662, 2019). "Likewise, genetically modified CXCR2+ T cells displayed increased in vivo migration in murine melanoma models." (PMID 30319622, 2018). "Thus, pharmacologically inhibiting CXCR2 signaling represents an attractive therapeutic approach that would prevent IL-1β–activated fibroblasts from protecting melanoma cells from MAPK inhibition." (PMID 28450382, 2017). "Altogether, these data demonstrate the potential in therapeutically targeting CXCR2 in melanoma." (PMID 28450382, 2017). "We show that cross talk between melanoma cells, macrophages, and fibroblasts initiates an IL-1 signaling cascade that generates a CXCR2-stimulating secretome, which ultimately leads to enhanced melanoma cell survival in the presence of MAPK signaling inhibition, via BCL2 up-regulation." (PMID 28450382, 2017). "This suggests that targeting CXCR2 in combination with MAPK signaling could improve initial responses to MAPK inhibitors in melanoma patients." (PMID 28450382, 2017). "This might reflect the potency of gene ablation compared with drug antagonism or that IL-1 has pleiotropic effects on tumor growth in addition to initiating CXCR2 signaling in melanoma cells." (PMID 28450382, 2017). "Thus, to test the effect of CXCR2 inhibition in vivo, we again used the 4434 allograft melanoma model." (PMID 28450382, 2017).
melanoma (continued). "To our knowledge, however, CXCR2 signaling has not been previously implicated in promoting tolerance to MAPK signaling inhibition in melanoma; thus, we describe a novel mechanism by which cells can tolerate MAPK therapy." (PMID 28450382, 2017). "Overexpression of the receptors CXCR1 and CXCR2 in human melanoma cells increased cell proliferation and invasion in vitro and significantly enhanced tumor growth in vivo, thus demonstrating the importance of these receptors in melanoma tumor growth and progression." (PMID 24259307, 2013). "In addition, we have also shown that host CXCR2 plays a critical role in melanoma growth, angiogenesis, and experimental metastasis." (PMID 23342280, 2012). "CXCR2 is expressed on fibroblasts, melanomas, and neutrophils." (PMID 22518343, 2012). "Moreover, small molecule antagonists of CXCR2 have previously been used to inhibit the proliferation, survival and angiogenesis of human melanoma tumors grown in mice." (PMID 23029099, 2012). "Ectopic expression of CXCR1 or CXCR2 confers a more aggressive phenotype to melanoma cells." (PMID 19401689, 2009). "In this study, we hypothesised that CXCR1 and CXCR2 regulate melanoma tumour growth and progression." (PMID 19401689, 2009). "Hence, once again our data emphasise the importance of CXCR1 and CXCR2 expression in melanoma cells." (PMID 19401689, 2009). "Moreover, an increase in chemotaxis and chemoinvasion of human melanoma cells expressing CXCR1 or CXCR2 on stimulation with CXCL-8 was also observed." (PMID 19401689, 2009). "We have performed in vitro and in vivo functional assays to provide direct evidence for multiple overlapping roles of CXCR1 and CXCR2 in melanoma growth, tumourigenesis, motility and invasion in two cell line models (SBC-2, non-tumourigenic and A375P, low-tumourigenic)." (PMID 19401689, 2009). "In addition, our data demonstrated that the CXCL-8-induced and CXCR1- or CXCR2-dependent modulation of melanoma cell proliferation and migration was mediated through the ERK1/2 MAP kinase pathway." (PMID 19401689, 2009). "Moreover, it sustains and induces melanoma aggressiveness, via an autocrine pathway involving IL-8 and its receptor C-X-C motif chemokine receptor 2 (CXCR2) and recruits macrophages at the tumor site by inducing a M2 phenotype in in vivo zebrafish and mouse models of melanoma." (PMID 38755629, 2024). "Interestingly, after Cxcr2 ablation, Tfcp2l1, a key tumor suppressive transcription factor, was the only gene significantly induced with a log2 fold-change greater than 2 in these three different melanoma models." (PMID 37270599, 2023). "Notably, we also observed reduced expression of genes involved in growth, increased expression of genes involved in tumor suppression, and promotion of an anti-tumor immune environment when Cxcr2 was deleted in tyrosinase-expressing melanoma precursor cells during transformation." (PMID 37270599, 2023). "Moreover, combination therapy with anti-CD115 Abs and CXCR2 agonists might inhibit B16F10 melanoma in vivo by preventing the enrollment of granulocytic MDSCs and removing immature TAMs." (PMID 37525217, 2023). "In addition, anti-CXCR2 treatment in mesothelioma was shorter and less frequent than in melanoma due to a rapid mesothelioma progression that could be insufficient to decrease the tumor infiltration with CXCR2+ cells." (PMID 33578808, 2021). "Furthermore, upon the selective inhibition of CXCR2 on PMN-MDSC we observed a reduction of their migration to the tumor lesions and pre-metastatic sites associated with prolonged survival and reduction of distant metastasis in melanoma bearing mice." (PMID 33578808, 2021). "In addition to vascular endothelial growth factor (VEGF)-mediated signaling, it was shown that vasculature-derived IL-8 could signal through the C-X-C motif chemokine receptor 2 (CXCR2) receptor in melanoma cells to promote angiogenesis." (PMID 32455885, 2020).
melanoma (continued). "In addition, it has been found that CXCR1/CXCR2 axis increases melanoma resistance to chemotherapy." (PMID 30591657, 2018). "This approach not only prevents the recruitment of granulocytic MDSCs via CXCR2 blockade but also depletes TAMs through CSF1R inhibition, thereby disrupting immune evasion mechanisms within the melanoma microenvironment." (PMID 40399946, 2025). "Previously known as growth-regulated gene-α (Gro-α) and melanoma growth-stimulatory activity (MGSA), CXCL1 primarily signals through the CXC motif chemokine receptor 2 (CXCR2)." (PMID 40427171, 2025). "The significant inhibition of proliferation, migration, and invasion of melanoma cells by SCH‐527123 through the downregulation of CXCR1 and CXCR2 and suppression of the PI3K/AKT pathway suggests its potential as a therapeutic agent for melanoma." (PMID 40740483, 2025). "Once CXCL1 is secreted, it activates its receptor CXCR2, which further increases CXCL1 expression in malignant melanoma cells, as well as induces tumor cell proliferation." (PMID 38673949, 2024). "In vitro experiments have shown that a dual CXCR1/CXCR2 inhibitor, such as SCH-479833 and SCH-527123, has an anti-tumor effect on malignant melanoma." (PMID 38673949, 2024). "The corresponding ligand to CXCR1 and CXCR2, namely CXCL8, is overexpressed on various cancer cells, including melanoma." (PMID 37170733, 2023). "In mouse melanoma and CRC, CAFs secrete CXCL5 to bind to c-x-c motif chemokine receptor 2(CXCR2) on cancer cells." (PMID 36759842, 2023). "Importantly, we show that the CXCR1/CXCR2 antagonist, SX-682, accomplishes a similar reduction in melanoma tumor burden, establishes an anti-tumor immune microenvironment, and significantly alters the transcriptional profile of melanoma cells when delivered during the transformation process." (PMID 37270599, 2023). "Having established the importance of Cxcr2 in the development, growth, and TME of Braf/Pten melanoma tumors, we sought to evaluate the therapeutic potential of systemic CXCR1/CXCR2 inhibition." (PMID 37270599, 2023). "Another larger phase 2 trial combines CXCR2 and nerve growth factor receptor (NGFR) in CAR T cells to treat melanoma (NCT01740557)." (PMID 36366354, 2022). "For example, the small-molecule antagonists, SCH-527123 and SCH-479833, that target CXCR2/CXCR1 were found to inhibit colon cancer and melanoma by decreasing neovascularization and increasing apoptosis of tumor cells." (PMID 36612163, 2022). "The anti-CXCR2 therapy was able to delay the development of primary tumors and metastases in LN and distant organs by reducing the accumulation of PMN-MDSC in melanoma microenvironment." (PMID 33578808, 2021). "Inhibition of CXCR2 resulted in a decreased infiltration of tumors with PMN-MDSC and increased survival of melanoma bearing mice." (PMID 33578808, 2021). "The effect of CXCR2 inhibition on PMN-MDSC migration and tumor progression was studied in RET transgenic mice and in C57BL/6 mice after surgical resection of primary melanomas." (PMID 33578808, 2021). "In contrast to our findings in the melanoma mouse model, only very few PMN-MDSC infiltrating mesothelioma expressed CXCR2." (PMID 33578808, 2021). "Since CXCR2 was found to be expressed almost exclusively on PMN-MDSC, we aimed to further investigate its functional relevance in melanoma." (PMID 33578808, 2021). "It is well-known that interleukin-8 (IL-8), which regulates proliferation and metastasis in melanoma, and its receptors, CXCR-1 and CXCR-2, are expressed more in A375SM than in A375P." (PMID 32859054, 2020). "For example, CXCR4 receptor is expressed in tumors such as ovary, glioma, melanoma and renal, CXCR6 in prostate cancer, CXCR2 in melanoma and CCR6 in colorectal and pancreatic cancer." (PMID 32499779, 2020). "Neutrophils migrate into melanoma using the CXCR2 chemokine receptor in response to its ligands CXCL1, CXCL2, and CXCL5 expressed in melanoma." (PMID 30899263, 2019).
melanoma (continued). "In a melanoma model, the CXCR2 inhibitor Navarixin synergized with MEK inhibition whereas, in an ovarian tumor model, the CXCR2 inhibitor SB225002 improved the antiangiogenic therapy Sorafenib." (PMID 30894861, 2019). "The role of CXCL5 in recruiting CXCR2+ MDSC and TAN has also been shown in models of renal cell carcinoma (RCC), PDA, melanoma, and hepatocellular carcinoma (HCC)." (PMID 30319622, 2018). "SCH-527123 and SCH-479833, dual CXCR1/2 and CXCR2 antagonists, were shown to inhibit migration and proliferation of A375SM melanoma cells." (PMID 28129639, 2017). "These molecules render the tumor microenvironment and facilitate progression and metastatic dissemination of melanomas via autocrine and paracrine activation of CXCR1 and CXCR2 chemokine receptors." (PMID 28129639, 2017). "The key chemokines involved in TAN recruitment to murine melanoma signal via the CXCR1 and CXCR2 axes, including CXCL1, CXCL2, CXCL6 and CXCL8." (PMID 28435677, 2017). "Blocking IL-8 significantly impaired the proliferative effect of phEC-CM on human A375 melanoma cells, consisting with the inhibition of IL-8 receptors CXCR1 and CXCR2 by using specific small molecular inhibitor SB225002." (PMID 26762853, 2016). "In a screen of several melanoma cell lines it was detected that the expression of chemokine receptors CCR7, CCR10, CXCR1, CXCR2 and CXCR4 can dramatically increase the rate of metastases and define their preferential site." (PMID 26197340, 2015). "Our previous studies have shown that exogenous CXCL-8 stimulated extracellular signal-regulated kinases (ERK) phosphorylation in melanoma cell lines, which is involved in CXCR1- or CXCR2-mediated cell growth." (PMID 23342280, 2012). "Our recent studies have demonstrated that CXCR1 and CXCR2, receptors of CXCL-8, are functionally involved in melanoma progression." (PMID 23342280, 2012). "The expression of CXCL8 in melanoma, as well as its receptors CXCR1 and CXCR2, has demonstrated a positive correlation with disease progression." (PMID 24212647, 2011). "CXCL8, acting as an autocrine/paracrine growth factor, influences the process of melanoma progression by activating its receptors, CXCR1 and CXCR2." (PMID 24212647, 2011). "Our data demonstrated that CXCR1- or CXCR2-overexpressing SBC-2 and A375P melanoma cells had enhanced proliferation, chemotaxis and invasiveness in vitro." (PMID 19401689, 2009). "The aggressiveness of malignant melanoma is attributed, in part, to the expression of CXCL-8 and its receptors, CXCR1 and CXCR2." (PMID 19401689, 2009). "The chemokines CXCL1 (Gro-α) and CXCL8 (IL-8) are constitutively produced by melanoma cells and the corresponding receptors CXCR1 and CXCR2 are expressed on melanoma cells as well as on macrophages, neutrophils and eosinophils." (PMID 16052222, 2005). "The chemotactic response of melanoma cells to IL-8 was mediated by CXCR1, and the mitogenic activity of IL-8 was mediated by both CXCR1 and CXCR2 in colon cancer, but only by CXCR1 in monocytes." (PMID 15545974, 2004). "In this study, we evaluated the effectiveness of the CDK4/6 inhibitor, palbociclib, the CDK2 inhibitor, PF-07104091, the dual CXCR1 and CXCR2 (CXCR1/2) antagonist, SX-682, and the combination of these inhibitors for effective treatment of melanoma in preclinical models." (PMID 40904502, 2025). "The chemokine receptors CXCR1 and CXCR2 are expressed on granulocytes, monocytes, mast cells, NK cells, neutrophils, basophils, CD8+ Teff cells and endothelial cells, whereas being overexpressed in melanomas." (PMID 37170733, 2023). "In addition to the effect of the CXCR1,2/CXCL8 axis in melanoma cells, it also plays an essential role in immune regulation as CXCR1 and CXCR2 are expressed on neutrophils, correlating with poorer prognosis and poor response to checkpoint inhibition." (PMID 37170733, 2023).